VDR (vitamin D receptor)
Diseases named in the same sentence as VDR in open-access papers (continued):
Sharing a sentence is not in itself a finding about the gene and the disease.
lumbar disc degeneration (7 papers, 2017 to 2025). "So, the aim of this study, was to investigate the relation between aggrecan gene VNTR and VDR gene rs731236 (TaqI) polymorphisms and lumbar intervertebral disc degeneration in a population in the North of Iran." (PMID 35919638, 2022). "For example, variations in the vitamin D receptor (VDR) have been associated with differing IDD risks across ethnic groups, while the THBS2 gene has been linked to lumbar disc degeneration." (PMID 40654524, 2025). "The purpose of this study was to investigate the association of Vitamin D Receptor (VDR) gene polymorphisms and VDR levels with lumbar disc degeneration (LDD)." (PMID 31127184, 2019). "After removing the duplicates, 33 records remained for screening, of which 19 were excluded (conference papers, records reporting VDR polymorphisms in lumbar disc degeneration, and records without any information on VDR polymorphisms)." (PMID 40428840, 2025).
lung adenocarcinoma (7 papers, 2018 to 2025). A carcinoma that arises from the lung and is characterized by the presence of malignant glandular epithelial cells. "Increased VDR expression in lung adenocarcinoma is associated with improved survival." (PMID 36101414, 2022). "We found that VDR expression was elevated in LUAD (lung adenocarcinoma) patients compared to normal lung tissues." (PMID 40872626, 2025). "Importantly, it has been shown that tumor progression may be correlated with lower VDR levels in different types of cancer, and a positive association between expression of VDR/calcitriol with improved prognosis was found in patients with lung adenocarcinoma." (PMID 33133014, 2020). "Recent studies have demonstrated that VDR is regulated by ubiquitination, and E3 ubiquitin ligase MDM2 mediates the ubiquitination degradation of VDR in lung adenocarcinoma cells." (PMID 38514643, 2024).
lupus nephritis (7 papers, 2013 to 2024). Glomerulonephritis in the context of systemic lupus erythematosus. "An association was reported between VDR BsmI BB genotype and lupus nephritis (P = 0.001)." (PMID 38160213, 2024). "However, the VDR B allele was associated with the development of nephritis in a Han Chinese population, and the bb genotype was associated with lupus nephritis in a Japanese population." (PMID 23065277, 2013). "Additional evidence corroborating this finding encompass the expression of the 25-(OH)D receptor (VDR), which has been examined in kidney biopsy specimens, revealing that VDR expression was decreased in kidney biopsy samples from patients with lupus nephritis." (PMID 39727649, 2024).
Arrhythmia (6 papers, 2018 to 2025). Any cardiac rhythm other than the normal sinus rhythm. "There is evidence that the VDR is expressed in human cardiomyocytes and so it is possible that large bolus dose vitamin D supplementation could adversely influence arrythmia incidence." (PMID 39275206, 2024). "For example, VDR is proven to be with the function of regulating vasodilatation; ADRB1 (Beta-1 adrenergic receptor) and ADRB2 (Beta-2 adrenergic receptor) serve as the vital role in the pathology and biology process of arrhythmia." (PMID 29321678, 2018).
autism spectrum disorder (6 papers, 2018 to 2025). A spectrum of developmental disorders that includes autism, and Asperger syndrome. "Certain polymorphisms in the vitamin D receptor gene are a risk factor for the childhood autism spectrum disorder." (PMID 29581796, 2018).
dementia (6 papers, 2014 to 2025). Loss of intellectual abilities interfering with an individual's social and occupational functions. "We, therefore, believe the findings of this longitudinal cross‐sectional study, which is supplementation vitamin D exacerbates dementia, may better align with our hypothesis that non‐genomic VDR signaling might contribute to the promotion of dementia." (PMID 35822270, 2022). "Third, the current study did not account for vitamin D binding proteins and vitamin D receptor genes; hence, we are unable to assess the relationship between bioavailable vitamin D levels and dementia risk." (PMID 35025861, 2022). "Thus, it could be that dementia‐related toxic amyloid formation elicits xenobiotic responses through non‐genomic VDR signaling." (PMID 35822270, 2022). "Recently, it has been shown that supplementation with vitamin D3 stimulates the vitamin D receptor (VDR), which potentially contributes to neuroprotection in dementia and neurodegenerative diseases." (PMID 40358165, 2025).
fracture (6 papers, 2021 to 2026). "Therefore, it seems clear that the F allele of the FokI polymorphism is associated with greater VDR activity, improving the response to vitamin D and calcium supplementation and being associated with the risk of bone fracture." (PMID 35057541, 2022).
glioblastoma (6 papers, 2020 to 2025). The most malignant astrocytic tumor (WHO grade IV). "Although VDR expression is increased in human glioblastoma (GB) cells, high VDR expression in GB is associated with 1,25-D treatment success." (PMID 38846332, 2024). "Current evidence also highlights vitamin D’s potential dual role in treating and preventing glioblastoma, supporting the clinical application of vitamin D or VDR as novel biomarkers in this context." (PMID 40699718, 2025). "miR-27b, which is overexpressed in BCa, has been shown to inhibit PPARγ and vitamin D receptor (VDR) in glioblastoma, reducing tumor progression." (PMID 40806474, 2025). "VDR knockdown inhibited the growth of glioblastoma and T-ALL cells, and lung metastatic cancer growth was extremely reduced in VDR-null mice." (PMID 37880985, 2024).
HIV-1 infection (6 papers, 2011 to 2024). The type species of lentivirus and the etiologic agent of acquired immunodeficiency syndrome (AIDS). "Elevated levels of vitamin D and the vitamin D receptor (VDR) have been implicated in contributing to innate resistance against HIV-1 infection." (PMID 38845818, 2024). "High levels of VitD and VDR expression are also associated with natural resistance to HIV-1 infection." (PMID 29593721, 2018). "Additionally, genetic variants related to high VitD and VDR function have been associated with susceptibility to HIV-1 infection, suggesting a potential pathogenic role of the VitD/VDR axis." (PMID 24349345, 2013). "Epigenetic repression of the VDR promoter via Snail has previously been described in the context of HIV-1 infection." (PMID 36146811, 2022). "In addition, the expression of VDR is positively correlated with the expression of several anti-HIV molecules [such as elafin, TRIM5, cathelicidin microbial peptide (CAMP), HAD-4, and RNase7], which are linked to natural resistance to HIV-1 infection." (PMID 29593721, 2018). "The VitD/VDR axis has strong immunomodulatory and antimicrobial effects and could play an important role modulating the risk of HIV-1 infection; however, reports on the influence of this axis on HIV-1 infection are contradictory." (PMID 24349345, 2013).
Hypercholesterolemia (6 papers, 2015 to 2023). An increased concentration of cholesterol in the blood. "However, Shamsuzzaman and colleagues showed that VDR deficiency in an ApoE−/− background combined with high fat diet (HFD) feeding protected mice against hypercholesterolemia-induced VC, even though they did develop atherosclerotic lesions." (PMID 34204304, 2021). "The fact that under conditions that normally lead to VC (i.e., hypercholesterolemia or supraphysiological vitamin D levels) VDR absence prevents VC development has shed some doubts on the results from the study of Schmidt and co-workers." (PMID 34204304, 2021). "Both apoE-/- and apoE-/-VDR-/- mice developed marked hypercholesterolemia, with a similar lipid profile within each gender." (PMID 26322890, 2015).
influenza (6 papers, 2016 to 2025). An acute viral infection of the respiratory tract, occurring in isolated cases, in epidemics, or in pandemics; it is caused by serologically different strains of viruses (influenzaviruses) designated A, B, and C, has a 3-day incubation period, and usually lasts for 3 to 10 days. "1,25(OH)2D3 and VDR signalling play a similarly significant role in the lung epithelia, and their roles in modulating responses to influenza and respiratory syncytial virus have been characterised." (PMID 34638897, 2021). "Epidemiologic studies demonstrate strong associations between seasonal variations in 25(OH)D levels and influenza infection, as well as response to vaccines as a result of variable VDR expression profiles." (PMID 27973447, 2016). "Finally, human cytomegalovirus induced a 88% inhibition of VDR expression in infected cells, leading to a gradual increase of the CYP27B1 gene to 970%; notably, no downregulation of the VDR was observed for influenza or adenovirus infection." (PMID 33897704, 2021).
ischemia (6 papers, 2017 to 2024). A hypoperfusion of the BLOOD through an organ or tissue caused by a PATHOLOGIC CONSTRICTION or obstruction of its BLOOD VESSELS, or an absence of BLOOD CIRCULATION. "Other studies have seen a beneficial effect in models of ischemia or traumatic brain injury by manipulating another vitamin D receptor, Protein Disulfide Isomerase A3 (PDIA3, Erp57)." (PMID 39275253, 2024). "In this study, we discovered that VDR in microglia/macrophages was pronouncedly upregulated in response to ischemia." (PMID 36890539, 2023). "Thus, VDR expression plays a significant role during retinal vascular development, especially during maturation of retinal vasculature by promoting PC quiescence and EC survival, and inhibition of ischemia-mediated retinal neovascularization by 1, 25(OH)2D3." (PMID 29272316, 2017). "A recent study demonstrated that the VDR is involved in attenuating ischemia-induced oxidative stress and brain injury via reciprocal activation of SMAD family member 3 (SMAD3) and VDR transcription factors." (PMID 36831327, 2023). "Compared to the sham group, both mRNA and protein levels of VDR were significantly increased in the ischemic hemispheres of the MCAO group, with a peak on day 3 and a subsequent decline on day 7 after ischemia." (PMID 36890539, 2023). "1,25-D3 activated the VDR, TGF-β1, TGF-β2, TGF-β3 and VEGF mRNA level induced by ischemia, while the increase was partially reversed by P5P treatment." (PMID 35369317, 2022).
lung diseases (6 papers, 2010 to 2025). "Vitamin D receptor (VDR) is extensively expressed in the lung, and the disrupted vitamin D/VDR axis may underlie various lung disorders." (PMID 41085609, 2025). "Among black patients, the Fok1 SNP in the VDR gene distinguished extrapulmonary from pulmonary disease." (PMID 20196868, 2010). "Besides, genetic polymorphisms in vitamin D receptor (VDR) and vitamin D-binding protein (VDBP) may also play a role in the pathogenesis of lung diseases." (PMID 36747237, 2023).
malaria (6 papers, 2012 to 2023). Malaria is a serious and sometimes fatal disease caused by a parasite that commonly infects a certain type of mosquito which feeds on humans. "More studies are required to identify VDR polymorphisms that are associated with malaria." (PMID 38099246, 2023). "This study identified NRAMP1, IFNG, NOS2A, MBL, VDR, and certain TLR-associated genes as important for susceptibility to TB and malaria, and the list has been growing ever since." (PMID 28881572, 2017). "In a mouse model of malaria, infection with Plasmodium chaboudi up-regulated VDR gene expression, suggesting that VDR may regulate malaria infection." (PMID 30897154, 2019). "Therefore, targeting VDR as potential therapeutics for malaria might be challenging." (PMID 38099246, 2023). "VDR has both positive and negative effects on malaria infected individuals." (PMID 38099246, 2023).
metastatic disease (6 papers, 2013 to 2024). "We also analyzed VDR expression in relation to the non–classic differentiations (NDs, defined in Experimental Section), which reflected the capacity for multidirectional differentiation and greater risk of metastatic disease and death." (PMID 26501255, 2015). "Since both astemizole and calcitriol inhibit EAG1 activity and expression, respectively, patients bearing EAG1 and VDR-positive solid or metastatic tumors may benefit from this EAG1 double blocking strategy." (PMID 25280486, 2014).
non-Hodgkin lymphoma (6 papers, 2012 to 2025). Distinct from Hodgkin lymphoma both morphologically and biologically, non-Hodgkin lymphoma (NHL) is characterized by the absence of Reed-Sternberg cells, can occur at any age, and usually presents as a localized or generalized lymphadenopathy associated with fever and weight loss. "The mechanisms by which vitamin D could confer protection against Hodgkin’s and non-Hodgkin’s lymphoma were studied through the examination of VDR polymorphisms in human populations." (PMID 35053549, 2022). "We aimed to investigate the expression of vitamin D receptor as a possible diagnostic marker and potential therapeutic target in HL as well as in B-cell derived non-Hodgkin lymphoma (B-NHL)." (PMID 22672495, 2012). "Similar to NCF1 and MMP-9, VDR is linked to modulation of immune cell function and considered a specific marker for HL, but not of B-cell derived non-Hodgkin lymphoma." (PMID 41296384, 2025). "In follicular low grade non-Hodgkin’s lymphoma (NHL), low levels of VDR expression was detected in primary tumor cells and cell lines (SU-DHL4 and SU-DUL5), however high concentration of VD3 was used to produce growth restriction in vitro." (PMID 30961641, 2019).
non-melanoma skin carcinoma (6 papers, 2013 to 2024). "Fewer studies have investigated the association of these VDR polymorphisms with non-melanoma skin cancer risk." (PMID 33255834, 2020). "As far as we are aware, no previous studies have involved a Spanish population to assess the possible associations between VDR polymorphisms and non-melanoma skin cancer." (PMID 33255834, 2020). "A comparison of the frequencies of the VDR genotypes in patients older than 70 years vs. 70 years or younger also revealed age-dependent variations in patients with non-melanoma skin cancer." (PMID 33255834, 2020). "Its receptor, the Vitamin D Receptor (VDR), is a direct target of the proto-oncogene ΔNp63α, which is overexpressed in non-melanoma skin cancers." (PMID 26068789, 2015). "ΔNp63α, a proto-oncogene, is up-regulated in non-melanoma skin cancers and directly regulates the expression of both Vitamin D receptor (VDR) and phosphatase and tensin homologue deleted on chromosome ten (PTEN)." (PMID 25191969, 2014). "Through its ability to induce VDR, ΔNp63α could enhance 1,25(OH)2D3 signaling in non-melanoma skin cancers." (PMID 25191969, 2014). "Although the epidemiologic evidence that adequate vitamin D nutrition protects against non-melanoma skin cancer (NMSC) is limited, recent evidence that the vitamin D receptor (VDR) is protective is compelling." (PMID 24202452, 2013).
nonalcoholic steatohepatitis (6 papers, 2018 to 2025). "VDR is widely expressed in the liver and inflammatory cells of chronic liver disease patients and its expression is negatively associated with the severity of liver histology in both nonalcoholic steatohepatitis (NASH) and chronic hepatitis C (CHC) patients." (PMID 35629892, 2022). "This randomized, placebo-controlled, parallel clinical trial was therefore designed to examine the effects of vitamin D supplementation on serum levels of VDR, fibrogenic factors, and fibrogenic MiRs in NAFLD patients with non-alcoholic steatohepatitis (NASH)." (PMID 30832722, 2019). "However, VDR activation in non-parenchymal liver cells like Kupffer or hepatic stellate cells could exert anti-inflammatory and anti-fibrotic effects, and consequently prevent NAFLD progression to nonalcoholic steatohepatitis and fibrosis." (PMID 32213983, 2020).
oral squamous cell carcinoma (6 papers, 2014 to 2026). "A significant association was detected between the VDR Taq I heterozygous Tt genotype and an increased risk of oral squamous cell carcinoma (OSCC)." (PMID 37242229, 2023). "Immunohistochemical analyses of human and murine oral squamous cell carcinomas showed increased VDR expression." (PMID 24626468, 2014).
ovarian tumor (6 papers, 2015 to 2024). "There have been reported that the expression of VDR is decreased in colorectal adenocarcinoma and renal clear cell cancer and increased in breast invasive carcinoma, ovarian tumor, and thyroid papillary carcinoma." (PMID 38639057, 2024). "In this study, we analyzed the expression of RORα, RORγ, and VDR in ovarian tumor cells and identified an inverse correlation between their expression and a more aggressive phenotype and unfavorable clinical outcome." (PMID 33227893, 2020). "As a critical mediator of the anti-cancer activity of vitamin D, VDR is highly expressed in ovarian tumor tissues." (PMID 32230936, 2020). "The data suggested that vitamin D treatment strategies play their protective roles in ovarian tumor progression, by increasing VDR expression." (PMID 27548154, 2016). "Moreover, VDR levels on platelets have been found to be higher in patients with ovarian tumours compared to healthy women and higher in women with ovarian malignancies compared to benign ovarian tumours." (PMID 32024052, 2020). "Importantly, the decreased expression of RORγ and VDR in ovarian tumor cells correlates with a more aggressive behavior and negative patient outcome." (PMID 33227893, 2020). "Interestingly, VDR has been found to be upregulated in ovarian tumors when compared with nonmatched normal ovarian tissue." (PMID 26000308, 2015).
pancreatic ductal adenocarcinoma (6 papers, 2014 to 2023). An infiltrating adenocarcinoma that arises from the epithelial cells of the pancreas. "Synergistic autophagy blockade and VDR signaling activation enhance stellate cell reprogramming in pancreatic ductal adenocarcinoma." (PMID 37409253, 2023). "Synergistic autophagy blockade and VDR signaling activation enhance stellate cell reprogramming in PDAC in pancreatic ductal adenocarcinoma." (PMID 37409253, 2023). "VDR negatively regulates Forkhead box M1 (FOXM1) signaling and further suppresses the development of pancreatic ductal adenocarcinoma." (PMID 33614641, 2021).
papillary thyroid cancer (6 papers, 2020 to 2025). "A previous study revealed that the knockdown of the VDR attenuated the antiproliferative, pro-apoptotic, and anti-invasive effects of vitamin D in papillary thyroid cancer (PTC) cells, potentially through the activation of the Wnt/β-catenin signaling pathway." (PMID 41150758, 2025). "The results showed that the expression of VDR was up-regulated in classical thyroid papillary carcinoma, tall thyroid papillary carcinoma and follicular thyroid papillary carcinoma." (PMID 38639057, 2024). "Meanwhile, the expression and role of VDR were experimentally validated in papillary thyroid cancer (PTC)." (PMID 38639057, 2024). "A more recent study also identified elevated VDR protein and mRNA expression in papillary thyroid carcinoma compared to healthy and benign thyroid tumours." (PMID 35807774, 2022). "In addition to increased expression of the vitamin D receptor (VDR) (responsible for mediating 1,25(OH)2D cellular actions) in papillary thyroid cancers, activity of the gene encoding CYP24A1 has also been found to be increased." (PMID 35807774, 2022). "Also, vitamin D receptor (VDR) expression has been demonstrated in normal thyroid tissue and papillary thyroid cancer." (PMID 33271814, 2020).